ILK (integrin linked kinase)
Diseases named in the same sentence as ILK in open-access papers (continued):
Sharing a sentence is not in itself a finding about the gene and the disease.
tumor (continued). "Different critical immunosuppressive factors in the TME show positive association with ILK expression including CAFs, Tregs and M2 macrophages infiltration as well as PD-L1 expression in a tumor-specific tumor manner." (PMID 35692780, 2022). "ILK is implicated in tumorigenesis, since its knockdown in hepatocellular carcinoma cells as well as ovarian cancer cells impairs tumor growth in mouse model." (PMID 34163519, 2021). "In baseline tumor specimens, highly expressed ILK mRNA is associated with poor prognostic factors for patient-free survival in the univariate and multivariate Cox regression models." (PMID 34976811, 2021). "The interactions between tumor cells and the extracellular environment are regulated by an integrin-linked kinase (ILK) to promote cell proliferation, migration, and EMT." (PMID 34976811, 2021). "Developing a similar understanding of response to ILK inhibition requires better understanding of the genetic alterations that predispose an individual’s tumor to respond." (PMID 33256002, 2020). "ILK expression and activity have been revealed to be increased in association with the tumor grade, T status, lymph node metastasis and survival rate of lung cancer patients." (PMID 30636169, 2019). "ILK (integrin-linked kinase) is a critical negative regulator of the Hippo tumor suppressor pathway, which can prevent Merlin dephosphorylation and activation by suppressing MYPT1, resulting in the nuclear accumulation of YAP/TAZ." (PMID 30961610, 2019). "Its expression has been associated with advanced tumor and through its interaction with β1-integrin, ILK responds to matrix stiffness activating an ILK/PI3K/Akt pathway, leading to up-regulation of self-renewal capacity in CSCs." (PMID 28209166, 2017). "Where integrin linked kinase (ILK) has been implicated in carcinogenesis, ILK-intestinal epithelial cell knockout mice showed reduced tumour growth and MMP-9 expression in experimentally induced CAC." (PMID 25948887, 2015). "Integrin-linked kinase (ILK) is a serine/threonine protein kinase, involved in the regulation of cell growth/survival, cell cycle progression, invasion and migration and tumor angiogenesis." (PMID 23599801, 2013). "Integrin-linked kinase (ILK) is a serine/threonine protein kinase involved in the regulation of tumor cell growth and angiogenesis." (PMID 23599801, 2013). "Integrin-linked kinase activity in the endothelium or in tumor cells is essential for physiological and pathological angiogenesis." (PMID 19924294, 2009). "The tumour-promoting phenotype of macrophages, M2 polarization, in vitro was impaired by the ILK deficiency and the number of M2-specific marker CD206-expressing tumour-associated macrophages (TAMs) in vivo were significantly diminished in myeloid-ILK deficient mice." (PMID 38077324, 2023). "Thus, the results showed that ILK expression is potentially associated with the infiltrating immunosuppressive cells as well as their markers and that is possibly tumor specific." (PMID 35692780, 2022). "miR-542-3p is a negative regulator of CRC, while integrin-linked kinase could contribute to tumor progression and chemoresistance." (PMID 35427373, 2022). "The nanoparticle-mediated delivery of ITGA9 siRNA into tumor cells has the capacity to sharply down-regulate angiogenesis, growth and metastasis by inducing β-catenin degradation via the integrin-linked kinase (ILK)/protein kinase A (PKA)/glycogen synthase kinase 3 (GSK3) pathway." (PMID 33790909, 2021). "Direct evidence for the significance of ILK expression in tumour-associated ECs is still missing." (PMID 33573141, 2021). "Overexpression of ILK is associated with tumor growth, invasion, and metastatic tumors." (PMID 35317111, 2021).
tumor (continued). "ILK has been implicated as a mediator in both inflammation and tumor growth." (PMID 34163519, 2021). "ILK (Integrin-linked kinase) which interacts with LIMS1 was also overexpressed in PDAC tumours." (PMID 33048956, 2020). "Finally, in another study performed in 96 phyllodes BC, ILK was found to be highly expressed in the tumor and associated with increasing tumor grade." (PMID 33043811, 2020). "Finally, ILK is found upregulated in BC tumor samples and its expression is associated with grade, stage, ER and PR status and metastasis." (PMID 33043811, 2020). "Integrin-linked kinase (ILK) promotes tumor growth and invasion." (PMID 15631637, 2005). "The putative oncogene, integrin-linked kinase (ILK) is a protein serine/threonine kinase that has been reported to regulate a number of biological properties including anchorage-independent cell cycle progression, tumour cell invasion and apoptosis." (PMID 12771992, 2003). "Furthermore, analysis of HGSOC tumor microarray data using OvMark demonstrated an increased estimated risk of death in patients with higher than median Fzd7 and ILK combined expression levels compared with patients with lower than median Fzd7 and ILK expression levels." (PMID 38822429, 2024). "While tumours of all genotypes were predominantly low-grade adenocarcinomas, the proportion of tumours that progressed to high-grade adenocarcinomas was relatively higher in WT mice compared to their myeloid-ILK deficient counterparts, suggesting a role for myeloid-ILK in tumour progression." (PMID 38077324, 2023). "Therefore, ILK is also associated with breast carcinogenesis." (PMID 35477364, 2022). "posits ILK as a central mediator of stiffness‐dependent oncogenesis, our physiologically relevant co‐culture model reveals that in a complex tumor microenvironment, the cellular origin of the stroma is a critical variable." (PMID 41537745, 2026). "Recently, it was found that fully activated ILK in tumor cells can inhibit Snail degradation, resulting in increased Snail content in cells." (PMID 39258668, 2024). "Specifically, NETs-DNA first binds to CCDC25 on the surface of tumor cells, which in turn enhances the invasiveness of tumor cells by activating the prometastatic ILK-Parvb-RAC1-CDC42 signaling cascade." (PMID 38369519, 2024). "Our findings indicate that in EC patients having undergone NRCHT+R, the overall expression of FAK, HIF-1α, Ki67, and CD44 was higher in tumor nests, whereas ILK was higher in tumor stroma." (PMID 38727811, 2024). "Our findings indicate that the overall expression of FAK, HIF-1α, Ki67, and CD44 was higher in tumor nests, whereas that of ILK was higher in tumor stroma." (PMID 38727811, 2024). "In vitro knockdown of ILK and Rictor suppresses TGFβ1-induced EMT in tumor cells, highlighting the fundamental role of the ILK/Rictor complex in mediating this process." (PMID 38339294, 2024). "Following interaction with NET-DNA, this receptor was reported to activate integrin-linked kinase (ILK) that in turn recruits β-parvin and initiates the RAC1–CDC42 cascade to induce cytoskeleton rearrangement and directional migration of tumor cells." (PMID 39430758, 2024). "In our cohort, a weak intensity of ILK was significantly more often found in a late tumor stage, whereas moderate or strong intensity was balanced between an early and late stage." (PMID 39685780, 2024). "We observed a markedly elevated expression of ILK in tumor clusters when compared to epithelial cells." (PMID 38191424, 2024). "While numerous studies have explored the expression levels of different molecules in tumor tissues, the current study aims to investigate the expression pattern of certain proteins (ILK, EphA2, and VEGFA) in a sample of LNs from CRC." (PMID 39525153, 2024). "As an important link to chronic inflammation, ILK has been correlated with tumor progression patterns and worse survival through its interaction with the extracellular matrix in other tumor types including NSCLC." (PMID 39685780, 2024).
tumor (continued). "Conversely, ILK-positive cells were highly expressed in the tumor stroma compared to the tumor nests." (PMID 38727811, 2024). "In those patients, a stronger expression of FAK+, CD44+, and ILK+ cells was found in tumor nests between the fiducial markers (former GTV) and beyond (former CTV), even after NRCHT." (PMID 38727811, 2024). "While the mechanistic details of ILK expression in myeloid cells are yet to be revealed, our study demonstrates a tumour-promoting role of myeloid-specific ILK expression." (PMID 38077324, 2023). "Overall, these results indicate a role of myeloid-ILK in tumour promotion through regulation of the tumour-infiltration of T cells either by restraining tumour-suppressing CD8+ T cells or by enhancing tumour-promoting FOXP3+ T cells." (PMID 38077324, 2023). "The tumour infiltration of CD206+ cells was significantly reduced in both AOM/DSS and APCmin/+-driven models of CRC, suggesting that ILK is required for the tumour promoting role of TAMs." (PMID 38077324, 2023). "ILK acts in various physiological and pathological processes, such as cell-matrix interaction, cell growth, proliferation, survival, differentiation, tumor metastasis, infiltration, and angiogenesis." (PMID 37630371, 2023). "Our results indicate that ILK is required for macrophage M2 polarization in vitro and the expression of M2-specific marker CD206 in tumour-associated macrophages (TAMs) in vivo." (PMID 38077324, 2023). "The downregulation of this marker in treated cells suggested the effectiveness of ILK inhibition in impeding tumor growth." (PMID 37887327, 2023). "Inhibiting ILK activity is an ideal strategy for tumor gene therapy and oncology drugs owing to its ability to induce cell cycle arrest and apoptosis." (PMID 37630371, 2023). "Particularly, ILK expression and activity are upregulated in various tumors and are crucial for tumor diagnosis." (PMID 37630371, 2023). "Overall, these observations show that ILK is an integral player in the tumour-promoting role of myeloid cells." (PMID 38077324, 2023). "In patient CRC tissue microarrays we observed elevated ILK+ myeloid (ILK+ CD11b+) cells in tumour sections compared to adjacent normal tissues, suggesting a conserved role for myeloid-ILK in CRC development in both human and animal models." (PMID 38077324, 2023). "A number of signal transduction pathways are regulated by ILK, which also forms a scaffold complex with cytoskeleton proteins, all of which are critical in the regulation of cell motility, tumor growth, and invasion." (PMID 35481240, 2022). "More specifically, it was found that ILK expression is negatively correlated with tumor purity in COAD, LUSC and STAD which in turn reflected significant positive associations with infiltration of CD4+ T cells, macrophages, neutrophils and DCs." (PMID 35692780, 2022). "On the other hand, such compound should be precisely delivered to tumor tissue as ILK and IPP are important for normal cells' proper functioning." (PMID 35089438, 2022). "In conclusion, periostin activates the proliferation and migration of tumor cells by the ILK/AKT/mTOR pathway." (PMID 35676936, 2022). "Interactions between the extracellular matrix and integrin complexes and activation of ILK are known prerequisites for activation of FAK in multiple tumor models." (PMID 35628269, 2022). "ILK overexpression in human CRC is associated with EMT and CSC traits, contributing to tumour progression and chemoresistance." (PMID 36117173, 2022). "ILK can be expressed in epithelial cells, tumor cells, fibroblasts, smooth muscle cells, and T cells." (PMID 35429970, 2022). "Taken together, ILK expression is upregulated in tumors and their adjacent non-tumor tissues supporting a role for ILK in regulating the TME and surrounding tissues." (PMID 35692780, 2022). "Suppression of ILK activity with specific inhibitors decreased tumor progression through G2/M phase arrest and apoptosis in glioblastoma cells." (PMID 35379935, 2022).
tumor (continued). "Involvement in those processes, coupled with its crucial role in epithelial–mesenchymal transition (EMT), invasion, and angiogenesis, indicated ILK as an attractive target for tumor treatment." (PMID 35089438, 2022). "Especially, signaling events downstream of β1 integrins involving focal adhesion kinase (FAK), integrin-linked kinase (ILK), and the phosphatidylinolsitol-3-kinase (PI3K)/Akt axis mediate radio- and chemoresistance in many tumor entities." (PMID 35194763, 2022). "The level of ILK was correlated with tumor grade (P = 0.005), TNM stage (P < 0.001), and invasion depth (P < 0.001), suggesting that it is correlated with tumor progression." (PMID 35379935, 2022). "Immunohistochemical analyses of 108 primary tumor tissues derived from lung cancer patients revealed that ILK was highly expressed in 30.6% (33/108) of tumors." (PMID 35379935, 2022). "Here we have discussed the extensive recent literature that implicates ILK in tumor progression, metastasis, and drug resistance." (PMID 35804980, 2022). "Rescue experiments showed that the overexpression of β-catenin reversed a tumor’s inhibition and apoptosis abilities induced by ILK knockdown." (PMID 35587162, 2022). "Here we have demonstrated that ILK is upregulated in tumors and their adjacent non-tumor tissues in CRC and high expression of ILK is associated with poor prognosis and advanced stages that are associated with invasion and metastasis." (PMID 35692780, 2022). "Here we have investigated expression of ILK in tumors and adjacent non-tumor tissues and correlated ILK expression with several TME factors in solid tumors, particularly in CRC where response to immunotherapy is unresolved." (PMID 35692780, 2022). "ILK mRNA expression in Oncomine CRC datasets comparing levels in normal tissues from either adjacent non tumor tissue or tissues from healthy individuals." (PMID 35692780, 2022). "As well, EMT induced by Twist or Snail increases expression of the pathway components, including ILK, demonstrating a link between EMT, tumor-initiating ability, and ILK signaling." (PMID 35804980, 2022). "In summary, elevated ILK is associated with poor prognosis in COAD and is upregulated in the TME and in the adjacent non-tumor tissues." (PMID 35692780, 2022). "In contrast, ILK does not show an association with immunosuppressive Treg and M2 cell infiltration, and their markers in KIRC suggesting the implication of ILK is dependent on tumor type." (PMID 35692780, 2022). "CDDP or PBS was intraperitoneally injected to observe the effect of changes in ILK expression on the tumor formation in nude mice." (PMID 35587162, 2022). "We showed that the primary tumors and their adjacent non-tumor tissues exhibit high expression not only of ILK but also immune and CAF gene signatures." (PMID 35692780, 2022). "In an orthotopic model of human prostate cancer, siRNA-mediated depletion of ILK reduced tumour growth and angiogenesis by inhibiting HIF1a and VEGF expression." (PMID 33573141, 2021). "The same pharmacological approach was used to suppress ILK expression in glioblastoma cells resulting in smaller tumours and reduced vessel density." (PMID 33573141, 2021). "What is necessary is further understanding of the function of ILK in epithelial and inflammatory cells during a senescence induction and investigation of the inflammatory senescence secretions and their effect on tumor growth." (PMID 34163519, 2021). "In thyroid tumour xenografts, pharmacological inhibition of ILK triggered apoptosis in both tumour cells and ECs, thus inhibiting tumour volume and angiogenesis." (PMID 33573141, 2021). "In tumor cells, the high expression of ILK can promote tumor angiogenesis and tumor progression by inducing VEGF expression." (PMID 33921219, 2021).
tumor (continued). "Results showed that the relative ILK mRNA expression was significantly higher in BC tissues compared to normal adjacent tissues while it was also correlated with tumor size, grade, stage, ER status, and lymph node metastasis." (PMID 33043811, 2020). "In this study, we demonstrate that MCP-1 promotes VEGF-A expression in OSCC by activating integrin-linked kinase (ILK) and MEK1/2 signaling and downregulating miR-29c expression, all of which subsequently enhances VEGF-A-induced tumor angiogenesis." (PMID 33330077, 2020). "In particular, the ILK and FAK signaling pathways impacting PI3K/Akt, MEK/ERK, and Jak/STAT signaling pathways have all be linked to anoikis resistance of tumor cells." (PMID 32632141, 2020). "Western blot with proteins extracted from tumor tissues confirmed the ILK knockdown and the inhibition of the downstream AKT phosphorylation." (PMID 33256002, 2020). "Downregulation of ILK using sgRNA resulted in reduced cell proliferation and tumor growth, confirming ILK as a valid therapeutic target." (PMID 33256002, 2020). "Among these canonical pathways, EIF2, oxidative phosphorylation, interferon signaling, integrin linked kinase (ILK) signaling, and JAK/STAT signaling were the top five most upregulated in tumor cells that received the vector expressing IL-27pepL." (PMID 32046108, 2020). "The tumor cell proliferation was lower in ILK sgRNA infected cells, matching the results observed with the tumor volume measurement." (PMID 33256002, 2020). "miR-625 targets ILK and suppresses invasion and metastasis, and miR-542-3p, which inhibits tumor progression, also targets ILK." (PMID 32751711, 2020). "Consistent with these, ILK overexpression suppresses anoikis, promotes cell and tumor growth as well as metastasis in vitro, and favors tumorigenicity in transgenic animals." (PMID 33043811, 2020). "ILK knockdown in SKOV3 cells results in tumor growth inhibition: To validate the findings obtained using a transient knockdown of ILK-1 using siRNAs, ILK was knocked down stably in SKOV3 cells using CRISPR/Cas9 sgRNA lentiviral constructs." (PMID 33256002, 2020). "Subcutaneous xenograft study to determine the effect of ILK knockdown on tumor growth was performed in NOD SCID gamma mice." (PMID 33256002, 2020). "In basal cell carcinoma, ILK expression leads to increased tumor invasiveness and EMT markers through upregulated Snail, β-catenin and α-SMA." (PMID 31440236, 2019). "Integrin-linked kinase (ILK), which is normally involved in regulating ECM signaling, leads to E-cadherin suppression and promotion of tumor invasiveness alongside a fibroblastic phenotype when aberrantly upregulated in EMT." (PMID 31440236, 2019). "Knockdown of ILK expression also impairs the migration of human umbilical vein ECs (HUVECs) toward VEGF and pharmacological ILK inhibition leads to reduced tumor growth and angiogenesis in a xenograft model." (PMID 31748531, 2019). "Previously, TMSB4X was reported to induce the EMT by activating integrin-linked kinase (ILK) and the TGF beta signalling pathway to promote tumour progression." (PMID 31781249, 2019). "Human tumor and nude mice xenograft tumor tissues showed the expression of ILK was increased while the expression of RI was inhibited." (PMID 27576342, 2016). "ILK expression was shown to be enhanced downstream of endothelin-1/endothelin A receptor signaling and inhibition of this signaling axis reduced tumor growth." (PMID 26959113, 2016). "Overexpression and constitutive ILK activation promotes tumor formation in transgenic mice and also provokes oncogenic cell transformation into anchorage-independent, highly migratory and invasive cells." (PMID 26959113, 2016). "HE staining and IF assay were conducted to further verify the influence of RI and ILK on tumor growth and metastasis." (PMID 27576342, 2016).